CNTN4 (contactin 4)
Diseases named in the same sentence as CNTN4 in open-access papers (continued):
Sharing a sentence is not in itself a finding about the gene and the disease.
ovarian carcinoma (1 paper, 2016). A malignant neoplasm originating from the surface ovarian epithelium. "Loss of heterozygosity (LOH) and gene sequencing analysis investigate the possibility of CNTN4 to function as tumor suppressor gene in ovarian cancer." (PMID 27259239, 2016).
pancreatic cancer (1 paper, 2018). "One is located upstream of CNTN4; the variant located near this gene was reported to be a risk factor for pancreatic cancer." (PMID 29923122, 2018).
pancreatitis (1 paper, 2018). Inflammation of the pancreas. "rs4437130, located upstream of the CTCN4 (contactin 4) gene, and rs62561366, located upstream of PTCH1 (patched 1), were nominally associated with thiopurine-induced pancreatitis." (PMID 29923122, 2018).
psychosis (1 paper, 2019). "The 3p26.3-loss, that covered CNTN4, was previously reported to be associated with psychosis in 22q11.2DS48." (PMID 30710087, 2019).
neurodevelopmental disorder (9 papers, 2016 to 2025). A behavioral and cognitive disorder with onset during the developmental period that involves impaired or aberrant development of intellectual, motor, or social functions. "Duplications of chromosome 3p that include contactin genes CNTN6 and CNTN4 have been reported to be associated with neurodevelopmental disorders." (PMID 40760574, 2025). "This is important since CNTN4 has previously been associated with neurodevelopmental disorders such as ASD." (PMID 38745463, 2024). "CNVs and structural rearrangements disrupting CNTN4 have been implicated in severe neurodevelopmental disorders such as ASD and DD." (PMID 27186239, 2016). "Although ASD-related phenotypes in Cntn4-deficient mice were observed, our findings do have relevance for neurodevelopmental disorder research." (PMID 26958094, 2016). "CNVs affecting CNTN4 are also thought to confer risk for various neurodevelopmental disorders." (PMID 29693535, 2018). "Interestingly, several groups reported that CNTN4 is associated with autism, a neurodevelopmental disorder." (PMID 29540662, 2018). "CNTN6 and CNTN4 encode for contacting proteins, which mediate cell surface interactions during nervous system development and have been suggested to be associated with neurodevelopmental disorders, though the association with nephrotoxicity needs to be further explored." (PMID 32617516, 2020).
tumor (6 papers, 2015 to 2025). "Additional pairs with a strong preference for tumor-to-tumor signaling in primary lesions include CNTN4-PTPRG, EFNA2-EPHA5, FGF6-FGFR4, FGF9-FGFR4, GDF11-ACVR2B, and INHBC-ACVR2B." (PMID 36676129, 2023). "Hence, we aimed to retrospectively collect pathologically identified PPGL tumor tissues from our center and investigate the expression of apelin and SUCLG2 along with previously studied ERBB-2, CNTN4, CHGB, and SDHB in metastatic and non-metastatic PPGLs." (PMID 35574028, 2022).
psychiatric disorder (4 papers, 2017 to 2024). A disorder characterized by behavioral and/or psychological abnormalities, often accompanied by physical symptoms. "Mutations in CNTN4 gene have been linked to various psychiatric disorders." (PMID 28821864, 2017).
neurological disorders (3 papers, 2010 to 2019). "Additionally, genes previously associated with neurological disorders were similarly up regulated, such as Mdga2, Clu, Epha3, Chl1, Cntn4, Cdh23, and Pard3b." (PMID 30628890, 2019).
CNTN4 also shares sentences with these, for which no sentence is quoted: cognitive disease (2 papers); Hearing impairment (2); alcohol dependence (1); anorexia nervosa (1); asthma (1); Ataxia (1); attention deficit-hyperactivity disorder (1); brain disease (1); cardiovascular disease (1); colorectal cancer (1); COVID-19 (1); dilated cardiomyopathy (1); epilepsy (1); heart failure (1); mental disorder (1); paraganglioma (1); Parkinson disease (1); peritonitis (1); personality disorder (1); pheochromocytoma (1); post-traumatic stress disorder (1); purine metabolic disorders (1); Rett syndrome (1); speech delay (1); Tourette Disorder (1).